NEDD4L (NEDD4 like E3 ubiquitin protein ligase)
Diseases named in the same sentence as NEDD4L in open-access papers (continued):
Sharing a sentence is not in itself a finding about the gene and the disease.
Intellectual disability (3 papers, 2023 to 2024). "For example, human orthologs to fly genes CASK (CASK), Mnb (DYRK1A), Dlg-1 (DLG1), Cdc42 (CDC42), Fmr1 (FMR1, FXR1/2), trio (TRIO), Nedd4 (NEDD4L/NEDD4) and CamKII (CAMK2A/B/D) have been linked to intellectual disability." (PMID 37759179, 2023). "The NEDD4L/RAC2/WASF1 may be a novel pathway associated with NEDD4L-related neurodevelopmental and intellectual disabilities." (PMID 39596003, 2024). "Pathogenic variants of NEDD4L can cause human paraventricular nodular heterotopia type 7 (PVNH7, OMIM # 617201), a neurological disorder characterized by abnormal neuronal migration during brain development with phenotypes of delayed psychomotor development, intellectual disability, and seizures." (PMID 39596003, 2024).
ischemic heart disease (3 papers, 2016 to 2024). "Other smoking-related hub genes found to overlap with coronary heart disease-related expression profile include NEDD4L, BCL2L1 and CDKN1A." (PMID 26837704, 2016). "First, the NEDD4L‐regulated angiogenic effect was not validated in pathological conditions in animal models, such as hind‐limb ischemia and ischemic heart disease." (PMID 38526036, 2024).
leukemia (3 papers, 2021 to 2024). A malignant (clonal) hematologic disorder, involving hematopoietic stem cells and characterized by the presence of primitive or atypical myeloid or lymphoid cells in the bone marrow and the blood. "NEDD4L has anti-proliferative effects on the leukemia cell line K562." (PMID 38027016, 2023).
adenoma (2 papers, 2013 to 2020). A neoplasm arising from the epithelium. "Loss of Nedd4/Nedd4l further promotes intestinal tumour progression to high‐grade adenomas in Apcmin tumour model." (PMID 31867777, 2020). "Consistently, loss of Nedd4 and/or Nedd4l resulted in an increase in Lgr5‐expressing stem cells in the adenomas." (PMID 31867777, 2020). "In contrast to the previous study, our data show that deletion of Nedd4 and/or Nedd4l in the intestinal epithelium alone is sufficient to accelerate adenoma development in Apcmin animals." (PMID 31867777, 2020). "On the other hand, the Wnt target gene Sox9 expression was significantly upregulated in all mutant adenomas when compared to control (Fig EV3G–J and O), suggesting that Wnt signalling is upregulated upon Nedd4 and Nedd4l loss." (PMID 31867777, 2020). "Conversely, NEDD4L (212445_s_at) expression decreased, trending downward in adenomas, and was significantly decreased in all stages of CRC." (PMID 24312311, 2013). "Interestingly, expression of Nedd4 was significantly upregulated in Apcmin adenoma, while Nedd4l expression was unchanged." (PMID 31867777, 2020). "Loss of Nedd4 and Nedd4l enhances ISC proliferation, increases sensitivity to RSPO stimulation and accelerates tumour development in Apcmin mice with increased numbers of high‐grade adenomas." (PMID 31867777, 2020). "Since deletion of Nedd4 and Nedd4l increases ISC numbers under homeostasis, we further examined the ISC marker Lgr5 expression in control and mutant adenomas." (PMID 31867777, 2020).
Anxiety (2 papers, 2016 to 2020). Intense feelings of nervousness, tension, or panic often arise in response to interpersonal stresses. "The novelty-suppressed feeding test showed that the latency to feed was markedly increased in defeated Sh-Nedd4l mice, indicating that knock down of Nedd4l in the mPFC attenuated stress-induced anxiety." (PMID 32703967, 2020).
atherosclerosis (2 papers, 2024 to 2025). A disease characterized by the build-up of fatty material and calcium deposition in the arterial wall resulting in partial or complete occlusion of the arterial lumen. "Some studies have proposed an association between NEDD4L, atherosclerosis, and other cardiovascular diseases." (PMID 40136477, 2025). "Recently, computational bioinformatics analysis identified NEDD4L as a key target gene associated with atherosclerosis occurrence, progression, and treatment." (PMID 40136477, 2025). "NEDD4L is significantly associated with the occurrence of atherosclerosis." (PMID 40136477, 2025). "In this scenario, NEDD4L has the potential as a diagnostic marker of a diabetic burden on endothelial cells, highlighting modifications with an endothelial ambiance that could predispose to enhanced atherosclerosis plaque formation." (PMID 40136477, 2025). "The results of the studies above are essential since they underscore NEDD4L as a potential candidate for intervening in atherosclerosis occurrence." (PMID 40136477, 2025). "Information, including study design and methods, intervention details, outcomes related to NEDD4L signaling against atherosclerosis, and study limitations and conclusions, was extracted from each study." (PMID 40136477, 2025). "Although the evidence is heterogeneous, most studies demonstrated that NEDD4L has detrimental effects on atherosclerosis plaque formation." (PMID 40136477, 2025). "Although NEDD4L is closely related to cardiovascular disease occurrence, evidence underscoring the relationship between NEDD4L signaling and atherosclerosis is primarily new." (PMID 40136477, 2025). "Anti-inflammatory drugs are also a class prominently related to NEDD4L-targeted therapies since anti-inflammatory agents can treat atherosclerosis-related inflammation." (PMID 40136477, 2025). "It systematically explores the impact of NEDD4L signaling on atherosclerosis occurrence and progression, integrating preclinical in vitro and in vivo models due to the current absence of clinical trials." (PMID 40136477, 2025). "In contrast, NEDD4L influences oxLDL uptake by polarized macrophages in blood vessels, preventing foam cell formation and atherosclerosis." (PMID 40136477, 2025). "This detailed exploration aims to enhance the understanding of NEDD4L’s multifaceted role in modulating atherosclerosis-related pathways." (PMID 40136477, 2025). "Our main objective was to identify, evaluate, and synthesize relevant preclinical research to examine the effects of NEDD4L signaling on atherosclerosis." (PMID 40136477, 2025). "We employed a systematic literature search methodology to comprehensively review the impact of NEDD4L signaling on atherosclerosis physiopathology across different models." (PMID 40136477, 2025). "A narrative synthesis was employed to integrate the findings and provide a comprehensive overview of NEDD4L’s effects on atherosclerosis occurrence across different models." (PMID 40136477, 2025). "Via further biochemical and biophysical analyses, the authors highlighted the detrimental effects of NEDD4L, which significantly interfered with atherosclerosis, increasing atherosclerosis plaque formation and interfering with disease progression." (PMID 40136477, 2025). "Our previous study has demonstrated that NEDD4L is involved in miR‐30a‐5p‐attenuated atherosclerosis by regulating macrophage polarization and lipid metabolism." (PMID 38526036, 2024). "Although most included studies underscored its deleterious potential, increasing atherosclerosis plaque formation, one study indicated that stimulating NEDD4L may positively counter atherosclerosis plaque formation." (PMID 40136477, 2025). "These authors treated HUVECs transfected with NEDD4L-siRNA and infected with NEDD4L-adenovirus to evaluate whether NEDD4L could regulate endothelial cell function to counteract atherosclerosis plaque formation." (PMID 40136477, 2025).
atherosclerosis (continued). "The main point of discussion from the included studies is whether NEDD4L’s effects on angiogenesis and endothelial function are detrimental to atherosclerosis." (PMID 40136477, 2025). "In addition, the results of the studies show that disrupting NEDD4L is a candidate therapy against atherosclerosis." (PMID 40136477, 2025). "Our results mainly demonstrate that NEDD4L is detrimental, increasing atherosclerosis occurrence." (PMID 40136477, 2025). "Most of the included studies underscored NEDD4L’s role in increasing atherosclerosis plaque formation, but other studies indicated that stimulating NEDD4L may positively counter atherosclerosis plaque formation." (PMID 40136477, 2025). "Our analysis of the included studies underscores that NEDD4L signaling may have heterogeneous effects on atherosclerosis." (PMID 40136477, 2025). "Our work may provide a scientific background for the pathogenesis and treatment of atherosclerosis based on NEDD4L targeting." (PMID 40136477, 2025). "Relevant studies investigated the impact of NEDD4L signaling on atherosclerosis." (PMID 40136477, 2025). "It has been discovered that NEDD4L overexpression can accelerate the migration, angiogenesis, and proliferation of human umbilical vein endothelial cells (HUVECs), facilitating the development of atherosclerosis." (PMID 40136477, 2025). "The broader medical community may be most interested in targeting NEDD4L and atherosclerosis using medicinal plants and bioactive compounds." (PMID 40136477, 2025). "Since atherosclerosis is also a prominent pathway in peripheral artery diseases, stimulating NEDD4L signaling in these patients may also be an effective strategy despite the current advancements in the field." (PMID 40136477, 2025). "Our recent work has proved that NEDD4L participated in miR‐30a‐attenuated atherosclerosis." (PMID 38526036, 2024). "Therefore, further research must focus on in vivo experiments to translate the findings into well-designed clinical trials to screen human individuals and promote the pharmaceutical design of products that could target NEDD4L in atherosclerosis therapy." (PMID 40136477, 2025). "However, other studies indicated that stimulating NEDD4L may positively counter atherosclerosis plaque formation." (PMID 40136477, 2025). "Regarding clinical applicability, it is worth noting that NEDD4L-targeted therapies could be integrated synergistically into existing treatment options and strategies against atherosclerosis, including statins, anti-inflammatory agents, and lifestyle modifications." (PMID 40136477, 2025). "NEDD4L-targeted therapies could enhance the anti-inflammatory potential of these drugs, therefore reducing pro-inflammatory cytokines more effectively and preventing macrophage polarization to the inflammatory pathway, leading to better atherosclerosis treatment results." (PMID 40136477, 2025). "However, it is known that the overexpression of NEDD4L-promoted protein kinase b (Akt) favors the phosphorylation of endothelial nitric oxide synthase (eNOS), which can impair the action of this enzyme, ultimately favoring the formation of atherosclerosis plaques under hyperlipidemic conditions." (PMID 40136477, 2025). "Their results demonstrated that NEDD4L promotes Akt, ERK 1/2, and eNOS phosphorylation, VEGFR2 expression, and angiogenesis, ultimately leading to endothelial cell migration and improved function, counteracting atherosclerosis." (PMID 40136477, 2025). "Nevertheless, despite previous efforts, no review has been published targeting the role of the NEDD4L gene in atherosclerosis plaque formation." (PMID 40136477, 2025). "At this stage, four records were excluded due to being a non-experimental paper, not involving NEDD4L signaling or being unrelated to atherosclerosis physiopathology, not being based on preclinical models, and not being in English." (PMID 40136477, 2025).
atherosclerosis (continued). "Systematic reviews, meta-analyses, and articles that did not focus on the relationship between NEDD4L and atherosclerosis and those unrelated to this health condition were excluded." (PMID 40136477, 2025). "In summary, while targeting NEDD4L may improve blood supply and tissue regeneration under lower blood flow, the risks associated with its use for promoting angiogenesis may not surpass the benefits due to its associations with atherosclerosis plaque stability and potential rupture." (PMID 40136477, 2025). "However, the evidence is dubious, and no review has yet synthesized the effects of targeting NEDD4L on atherosclerosis." (PMID 40136477, 2025). "However, NEDD4L’s effects on atherosclerosis plaque formation are dubious, and no previous review has summarized its actions." (PMID 40136477, 2025). "Additionally, until 2024, when three contemporary studies in the field were published, the evidence of the role of NEDD4L in atherosclerosis lacked comprehensive detail." (PMID 40136477, 2025).
brain tumors (2 papers, 2015 to 2022). "In addition, four other TSGenes are expressed at two- to eight-fold lower levels in T-ALL compared to brain tumors and/or B-ALL samples: NEDD4L, PLCB3, APC and ZMYND11." (PMID 35401501, 2022).
cardiomyopathy (2 papers, 2022 to 2024). A disease of the heart muscle or myocardium proper. "Rare PTVs in three prioritized genes, not established causes of cardiomyopathy, were found to be associated with binary diseases outcomes (MAP3K7 and NEDD4L with DCM) in at least one cohort and with quantitative traits (NEDD4L, MAP3K7 and SSPN) in UKB." (PMID 39572783, 2024). "This implies that SGK1 and Nedd4L are involved in the development of hyperglycemia-induced cardiomyopathy, future studies are warranted to validate whether targeting SGK1 and Nedd4L could provide a solution for the clinical treatment of diabetic cardiomyopathy or not." (PMID 35429991, 2022).
dyslexia (2 papers, 2010 to 2016). A learning disorder characterized by an impairment in processing written words. "Along with already published biological evidence, MC5R, DYM and NEDD4L make attractive candidates for dyslexia susceptibility genes." (PMID 21060895, 2010).
Hepatic fibrosis (2 papers, 2025 to 2026). The presence of excessive fibrous connective tissue in the liver. "Nedd4L is the only E3 ubiquitin ligase that regulates the progression of hepatic fibrosis in NAFLD by modulating key components of the TGF-β signaling pathway." (PMID 40292292, 2025).
immune deficiency (2 papers, 2018 to 2024). "Therefore, we concluded that downregulated NEDD4L in ccRCC might lead to metabolic disorder and immune deficiency, inhibit cell apoptosis, promote cell growth, migration, and adhesion, and further induce the development of ccRCC." (PMID 39596003, 2024).
injury (2 papers, 2024 to 2025). Damage inflicted on the body as the direct or indirect result of an external force, with or without disruption of structural continuity. "Downregulation of BiP by NEDD4L has been shown to suppress both apoptosis and ER stress induced by acute liver injury." (PMID 41162172, 2025). "In summary, our results indicate MCAO induced oxidative stress and iron accumulation in the brain, while NEDD4L knockout further augmented these effects and exacerbated ischemia-induced brain injury." (PMID 38302612, 2024).
interstitial lung disease (2 papers, 2017 to 2021). A diverse group of lung diseases that affect the lung parenchyma. "In the interstitial lung diseases (ILD) study, it was reported that ZEB-1 affects the persistence of disease in ILD through suppression of NEDD4L by miR-23a." (PMID 28362846, 2017).
oral squamous cell carcinoma (2 papers, 2023 to 2024). "Nevertheless, in a previous study on oral squamous cell carcinoma, NEDD4L overexpression suppressed proliferation, cell cycle transition and glycolysis and inhibited in vivo tumour growth." (PMID 38526036, 2024). "In oral squamous cell carcinoma, NEDD4L overexpression results in an increase in the number of G0/G1 cells and a decrease in the number of S-phase cells, indicating that NEDD4L triggers cell cycle arrest." (PMID 38027016, 2023).
pancreatic adenocarcinoma (2 papers, 2024). "In 2009, NEDD4L (also known as Nedd4-2) was identified as another ubiquitin ligase capable of interacting with both WT- and F508del-CFTR in CFPAC-1 cells (a pancreatic adenocarcinoma cell line from a patient carrying F508del-CFTR)." (PMID 38888668, 2024).
pneumonia (2 papers, 2022 to 2024). An acute, acute and chronic, or chronic inflammation focally or diffusely affecting the lung parenchyma, caused by an infection in one or both of the lungs (by bacteria, viruses, fungi, or mycoplasma.). "Insulin mitigates pneumonia by inhibiting NEDD4L, thereby boosting the expression of the epithelial sodium channel via the phosphatidylinositol 3‐kinase–protein kinase B (PI3K–Akt) pathway." (PMID 35355403, 2022).
renal carcinoma (2 papers, 2021 to 2024). A carcinoma arising from the epithelium of the renal parenchyma or the renal pelvis. "In NEDD4L CKO mice and ccRCC tissues, NEDD4L expression was inversely correlated with RAC2 expression, and NEDD4L directly reduced RAC2 protein levels, suggesting that aberrant NEDD4L expression may be a novel mechanism underlying RAC2 upregulation in renal cancer." (PMID 39596003, 2024). "In our study, it was found that the MAPK signal pathway was reduced in NEDD4L overexpressed renal carcinoma cells but activated in NEDD4L knockdown cells." (PMID 34539897, 2021). "Importantly, our data provided evidence for the first time from NEDD4L CKO mice and renal cancer Caki-1 cells supporting RAC2 as a novel ubiquitylation target of NEDD4L in ccRCC." (PMID 39596003, 2024). "NEDD4L may be involved in regulating the tumor immune microenvironment, and ubiquitinating and degrading key cell growth kinases to suppress the growth of renal cancer." (PMID 34539897, 2021). "Our data indicate that in renal cancer cells, NEDD4L may inhibit tumor cell growth by ubiquitinating multiple kinase molecules." (PMID 34539897, 2021).
acute myeloid leukemia (1 paper, 2021). Acute myeloid leukemia (AML) is a group of neoplasms arising from precursor cells committed to the myeloid cell-line differentiation. "However, the expression pattern and clinical implication of NEDD4L in acute myeloid leukemia (AML) remains poorly defined." (PMID 34809620, 2021).
AIDS (1 paper, 2024). A syndrome resulting from the acquired deficiency of cellular immunity caused by the human immunodeficiency virus (HIV). "Moreover, NEDD4L is also involved in Acquired Immune Deficiency Syndrome (AIDS)." (PMID 38785984, 2024).
asthma (1 paper, 2014). "These variants include a deletion in the intron of NEDD4L, which is a gene implicated in asthma by other genetic and functional evidence." (PMID 25116239, 2014). "We identified a nominally significant association (p = 0.03; Odds ratio (OR) = 3.13) between a 6 kbp deletion in an intron of NEDD4L and increased risk of asthma." (PMID 25116239, 2014). "Association of intronic deletion in NEDD4L with asthma in additional populations." (PMID 25116239, 2014). "A deletion in an intron of NEDD4L was present at 2.7% frequency in individuals with asthma and only at 0.9% in the controls (p = 0.03; Odds ratio (OR) = 3.13)." (PMID 25116239, 2014). "In addition, NEDD4L is under a linkage peak on chromosome 18 for asthma symptoms identified in the Hutterites." (PMID 25116239, 2014).
Cerebral ischemia (1 paper, 2024). Restriction of arterial blood supply to the brain associated with insufficient oxygenation to support the metabolic requirements of the tissue. "Taken together, these in vivo data definitively confirm that METTL3 mediates neuroprotection in cerebral ischemia through modulating the NEDD4L-TFRC axis to suppress iron-induced ferroptosis." (PMID 38302612, 2024).
cognitive decline (1 paper, 2023). "MYT1L gene, LRP1B gene and NEDD4L gene show strong associations with AD, and leading to cognitive decline in AD." (PMID 37510227, 2023).
Cognitive impairment (1 paper, 2024). Abnormal cognition is characterized by deficits in thinking, reasoning, or remembering. "LncRNA nuclear enriched abundant transcript 1 (NEAT1) interacts with NEDD4L and promote PTEN-induced putative kinase 1 (PINK1)’s degradation, thereby the interaction between them is assumed to be responsible for mitochondria dysfunction and cognitive impairment." (PMID 38368488, 2024).